ASPG (asparaginase)
Diseases named in the same sentence as ASPG in open-access papers (continued):
Sharing a sentence is not in itself a finding about the gene and the disease.
colon cancer (5 papers, 2019 to 2025). "The asparaginase-deficient strain demonstrated equivalent infectious burden both in vitro (organoids) and in vivo (colonic tumours)." (PMID 39558103, 2024). "A recent study carried out in SW480 and SW620 colon cancer cells lines, showed that chloroquine and asparaginase decrease asparagine levels, which subsequently retards cell growth and autophagy, and activates apoptosis." (PMID 32184446, 2020). "ASPG has also been identified as a prognostic biomarker for colon cancer in several studies." (PMID 41425595, 2025). "Asparaginase deprives cells of asparagine, which leads to cell death, and could be a potential valuable for treatment of women with colon cancer." (PMID 32184446, 2020). "One study analyzed asparaginase therapy in participants with a conglomerate of primarily solid tumors: melanoma, small cell lung cancer, non-small cell lung cancer, sarcoma, colon cancer, cholangiocarcinoma, renal cell carcinoma, bladder cancer, and malignancy with unknown primary." (PMID 36578934, 2022).
Hepatic failure (5 papers, 2020 to 2024). "We identified the induction period of treatment after six applications of asparaginase as a critical time point for severe hepatotoxicity; all three cases of liver failure were diagnosed after the sixth dose of L-Asp in the chemotherapy protocol." (PMID 34640436, 2021). "Two additional treatment‐related deaths occurred beyond induction therapy (one due to septic shock and one due to asparaginase‐induced hepatic failure), for an overall treatment‐related mortality (TRM) of 10%." (PMID 35844676, 2021). "Hepatic failure, like platelet decrease, may be related to anti-asparaginase antibodies such as IgG and IgE, which may also form and accumulate immune complexes and could be responsible for the increased organ size in WT- and P40S-enzyme-treated groups, unlike the S206C-exposed group." (PMID 38892196, 2024).
hepatocellular carcinoma (5 papers, 2021 to 2025). A malignant tumor that arises from hepatocytes. "Considering as chemotherapeutic candidate; U87 glioma and Huh7 hepatocellular carcinoma cells were treated with purified asparaginase of B. halotolerans ASN9 and significant anticancer activity with IC50 of 55 and 37 μg mL-1 were obtained, respectively." (PMID 38015853, 2023). "Therefore, T. viridel-asparaginase represents a promising therapeutic agent in hepatocellular carcinoma." (PMID 36995465, 2023). "An increase of GS protein but not GS mRNA was also observed in the fetal hepatoblastoma cell line HepG2 and in three hepatocellular carcinoma cell lines (Hep3B, Huh-7, PLC-PRF-7) treated with asparaginase." (PMID 34235580, 2021).
hypersensitivity (5 papers, 2019 to 2025). An inflammatory response to an exogenous environmental antigen or an endogenous antigen initiated by the adaptive immune system. "For instance, in a pediatric trial involving patients with hematologic malignancies who had not previously undergone PEGylated asparaginase treatment, three out of four patients experienced hypersensitivity reactions." (PMID 40871093, 2025).
T-cell lymphoma (5 papers, 2015 to 2025). "Currently, most recommended regimens for NK/T-cell lymphomas contain asparaginase or its pegylated form." (PMID 35158865, 2022). "Asparaginase has significant single-agent activity in relapsed/refractory (R/R) NK/T-cell lymphoma." (PMID 35158865, 2022).
anaphylaxis (4 papers, 2016 to 2023). An acute hypersensitivity reaction that occurs from exposure to an allergen. "Therefore, future studies with rationally timed longitudinal samples from more patients may more clearly define antigen-driven T-cell responses—particularly those with asparaginase-associated anaphylactic shock, where mediation strategies are more urgently required." (PMID 36980715, 2023).
chronic myeloid leukemia (4 papers, 2015 to 2025). "These articles primarily analyzed asparaginase therapy in ALL (n=23) with a smaller number reporting on AML (n=3), chronic myeloid leukemia in blast phase (n=1), and non-Hodgkin’s lymphoma (n=1)." (PMID 36578934, 2022).
Hyperammonemia (4 papers, 2019 to 2022). An increased concentration of ammonia in the blood. "The previously unrecognized acute phase of hyperammonemia associated with asparaginase infusion coincides with infusion reactions." (PMID 35997335, 2022). "Although asparaginase is associated with hyperammonemia, the magnitude of the increase in serum ammonia immediately after the infusion and in response to multiple infusions has not been examined." (PMID 35997335, 2022). "The increasing severity of infusion reactions of young pigs during and immediately after the administration of Erwinia asparaginase mimics the infusion reactions associated with hyperammonemia of patients treated with Erwinase and both native and pegylated forms of E. coli asparaginase." (PMID 35997335, 2022). "Notably, hyperammonemia caused by the deamination of asparagine and glutamine and the ensuing catabolism of other amino acids has been associated with asparaginase since the 1970s." (PMID 35997335, 2022). "The juvenile pig is a translational animal model for understanding the causes of acute and chronic hyperammonemia, differentiating from hypersensitivity reactions, and for improving infusion protocols to reduce acute hyperammonemia and to allow the continued use of asparaginase." (PMID 35997335, 2022). "Although normal or elevated blood urea nitrogen among patients with hyperammonemia associated with asparaginase imply a functional urea cycle, diminished capacities may be inadequate to rapidly clear the released ammonia, resulting in the increasing severity of acute hyperammonemia." (PMID 35997335, 2022). "The increasing severity of acute hyperammonemia and especially the significant difference between the first and last infusions indicate that multiple infusions of asparaginase progressively disrupt ammonia homeostasis." (PMID 35997335, 2022). "Individuals with urea cycle defects are characterized by hyperammonemia that can be fatal if asparaginase is administered." (PMID 35997335, 2022). "The study reported herein tracked the severity of infusion reactions and hyperammonemia resulting from providing 12 infusions of intravenous Erwinia asparaginase, using juvenile pigs used as a translational model for pediatric clinical patients." (PMID 35997335, 2022). "Non‐allergic hypersensitivity reaction and the hyperammonemia reaction can also occur during the asparaginase infusion." (PMID 34431241, 2022). "Differentiation between the contributions of acute hyperammonemia and hypersensitivity to infusion reactions is needed for decisions about appropriate interventions to continue asparaginase therapy and to maximize event-free survival." (PMID 35997335, 2022). "The acute and prolonged phases of hyperammonemia are partly explained by a combination of asparaginase activity, concentrations of substrates (asparagine and glutamine), and enzyme specificity." (PMID 35997335, 2022). "The prolonged phase of hyperammonemia is characterized by ammonia concentrations that exceed 50 μM for several days after the administration of asparaginase before declining in pigs (present study)." (PMID 35997335, 2022). "Of particular importance is why the severities of the acute and prolonged phases of hyperammonemia increase with continued asparaginase therapy." (PMID 35997335, 2022). "Effective interventions for hyperammonemia require understanding how asparaginase disrupts ammonia homeostasis." (PMID 35997335, 2022). "However, the onset, magnitude, and duration of the rapid increase in blood ammonia, herein termed acute hyperammonemia, and the potential contribution to the adverse reactions that occur during or shortly after asparaginase infusion are uncertain." (PMID 35997335, 2022). "The concurrence of hyperammonemia and infusion reactions was studied using weaned juvenile pigs that received 12 infusions of Erwinia asparaginase (Erwinase; 1250 U/kg) over 28 days, with two 5-day recovery periods without asparaginase after the eighth and eleventh doses." (PMID 35997335, 2022).
Hyperammonemia (continued). "Although hypersensitivity to Erwinase is less frequent than for the native and pegylated forms of E. coli asparaginase, the incidence of hyperammonemia may be higher, corresponding to a higher use of antiemetics." (PMID 35997335, 2022). "Our findings highlight that understanding how asparaginase disrupts ammonia homeostasis is tantamount to improving infusion protocols and interventions that will reduce the magnitude and severity of hyperammonemia and associated infusion reactions that are independent of immune responses." (PMID 35997335, 2022). "Although the biological half-life of asparaginase is extended through the PEGylation process, plasmatic asparagine and glutamine are hydrolyzed into ammonia, which may be responsible for the high incidence of symptomatic hyperammonemia in children with ALL receiving PEG-asparaginase." (PMID 34452229, 2021). "The potential contribution of hyperammonemia to adverse reactions was not fully recognized until after 2010, when the intravenous administration of asparaginase became increasingly common." (PMID 35997335, 2022).
hyperlipidemia (4 papers, 2017 to 2025). "Accordingly, hyperlipidemia induced by corticosteroids and asparaginase has been suggested to be associated with increased risk of ON, although most studies have been inconclusive." (PMID 28413626, 2017). "Hyperlipidemia, a common side effect of corticosteroids and asparaginase treatments, seems to be a contributing factor to ON." (PMID 41373522, 2025).
Hypoalbuminemia (4 papers, 2016 to 2024). The concentration of albumin in the blood circulation is below the lower limit of normal. "In this retrospective study of the role of serum albumin in 325 HDMTX 5g/m2 courses given to children with ALL we found that hypoalbuminemia was a frequent occurrence, apparently caused by preceding asparaginase therapy." (PMID 39305296, 2024). "We noticed that all patients in our study suffered from hypoalbuminemia and this may have been caused by peg-asparaginase." (PMID 35141162, 2022). "Hypoalbuminemia was present in 51% of the courses, mostly in the early phases of chemotherapy while asparaginase therapy is ongoing, and especially if given less than 2 weeks after a dose (78%)." (PMID 39305296, 2024). "Hypoalbuminemia coincided with parallel, ongoing asparaginase therapy." (PMID 39305296, 2024).
ovarian carcinoma (4 papers, 2015 to 2022). A malignant neoplasm originating from the surface ovarian epithelium. "Autophagy was also observed in ovarian cancer cell exposed to asparaginase at physiologically attainable concentrations with induction of ATG12, beclin-1, and cleavage of LC3." (PMID 25738356, 2015). "In ovarian cancer cells, ASNS silencing increased asparaginase sensitivity, which invokes the possibility in exploring ASNS as a biomarker for ovarian cancer treatment." (PMID 31681605, 2019).
sarcoma (4 papers, 2015 to 2024). A usually aggressive malignant neoplasm of the soft tissue or bone. "Analogous experiments confirmed that metformin or imiquimod also augmented the anti-proliferative (p < 0.01) and pro-apoptotic (p < 0.01) effects of asparaginase on human RD sarcoma cells." (PMID 33499165, 2021). "As complex 1 inhibitors significantly augmented the adverse effects of asparagine depletion of mouse sarcoma cells, human RD cells were exposed to combinatorial treatment with asparaginase and phenformin." (PMID 33499165, 2021). "Genetic silencing of ASNS combined with depletion of systemic asparagine via asparaginase decreased sarcoma growth in vivo." (PMID 33499165, 2021). "Our experiments revealed a clear synergistic effect of asparaginase and complex 1 inhibitors on the growth of mouse and human sarcomas, including patient-derived rhabdomyosarcoma cultures." (PMID 33499165, 2021). "Exogenous supplementation with aspartate partially reversed the growth-inhibitory effects of asparaginase on mouse sarcoma cells." (PMID 33499165, 2021). "Asparagine depletion of sarcoma cells can also be achieved by exposure to asparaginase (N-ase), an U.S. Food and Drug Administration (FDA)-approved drug which catalyzes the breakdown of asparagine and glutamine in medium with and without cells." (PMID 33499165, 2021). "Both amino sulfoximine 5 (AS5) and asparaginase reduced the proliferation of mouse and human sarcoma cell lines in vitro." (PMID 26499495, 2015). "However, when compared to lymphoblasts, asparaginase sensitivity of sarcoma cells is moderate to poor." (PMID 33499165, 2021). "Asparaginase was also shown to reduce the in vitro growth of sarcoma cells." (PMID 33499165, 2021). "Complex 1 inhibitors may be applied in combination with asparaginase to further exploit the anti-cancer effects of asparagine depletion in sarcomas." (PMID 33499165, 2021). "Of note, we also used four distinct primary human rhabdomyosarcoma cell cultures to confirm that simultaneous exposure to asparaginase and imiquimod significantly enhanced the anti-proliferative effects of either asparaginase or imiquimod alone in patient-derived low-passage sarcoma cells." (PMID 33499165, 2021). "Analogous to our observations in mouse sarcoma cells treated with asparaginase and complex 1 inhibitors, supplementation with the electron acceptor pyruvate reversed the anti-proliferative effects of asparaginase and phenformin alone and in combination on human RD cells (p < 0.01)." (PMID 33499165, 2021). "Indeed, asparaginase sensitivity of sarcoma cells is moderate to poor when compared to lymphoblasts." (PMID 33499165, 2021). "Also, asparaginase was previously shown to reduce the growth of mouse and human sarcoma cells." (PMID 33499165, 2021). "In this study, we interrogated changes in the sarcoma metabolome induced by asparagine depletion to better understand why cancer cells depend on adequate asparagine availability and to identify chemically actionable vulnerabilities that may be exploited to potentiate asparaginase effects." (PMID 33499165, 2021). "Asparaginase’s effects on the global metabolomic profile of mouse sarcoma cells grown with and without exogenously supplemented asparagine (100 mg/L) were investigated by GC-MS." (PMID 33499165, 2021). "We also report synergistic effects of asparaginase and complex 1 inhibitors, which block regeneration of nicotinamide adenine dinucleotide (NAD+) in the electron transport chain and enhance reductive stress in asparagine-starved sarcoma cells." (PMID 33499165, 2021). "Also, asparagine depletion via the ASNS inhibitor amino sulfoximine 5 (AS5) or asparaginase inhibited mouse and human sarcoma growth in vitro, and genetic silencing of ASNS in mouse sarcoma cells combined with depletion of plasma asparagine inhibited tumor growth in vivo." (PMID 26499495, 2015).
Thrombocytopenia (4 papers, 2016 to 2024). A reduction in the number of circulating thrombocytes. "Therefore, anti-asparaginase antibodies may cause thrombocytopenia, with the worst scenario observed in the WT group followed by the P40S enzyme, although no animals suffered from spontaneous bleeding." (PMID 38892196, 2024).
COVID-19 (3 papers, 2023 to 2025). A disease caused by infection with severe acute respiratory syndrome coronavirus 2. "Therapy for ALL/LLy is unique; it lasts approximately 2.5 years and can exacerbate COVID-19–related complications (eg, pancreatitis and thrombosis caused by asparaginase and obesity, diabetes, and lymphopenia-related severe viral infection associated with glucocorticoids)." (PMID 38363571, 2024). "Additionally, there are several drugs either recently used and suggested for COVID-19 treatment or included in the chronic medication of some of the patients whose cases have been reported, such as lisinopril, enalapril, pantoprazole, asparaginase, which are connected to the development of AP." (PMID 37189499, 2023).
Hepatic steatosis (3 papers, 2017 to 2025). Steatosis is a term used to denote lipid accumulation within hepatocytes. "Liver dysfunction as a result of oxidative stress and hepatic steatosis is an asparaginase-associated adverse event that complicates remission induction and reduces treatment success." (PMID 28455513, 2017). "The ISR is necessary to protect mice from hepatic steatosis, hepatotoxicity, and eventual death due to asparaginase exposure." (PMID 39798881, 2025).
hypercoagulable (3 papers, 2014 to 2021). "Asparaginase is known to promote thrombophilia by interfering with the coagulation system." (PMID 25317335, 2014).
Hypofibrinogenemia (3 papers, 2016 to 2025). Decreased concentration of fibrinogen in the blood. "Asparaginase induces hypofibrinogenemia and suppresses natural anticoagulants, thereby promoting thrombosis." (PMID 40978872, 2025).
lung adenocarcinoma (3 papers, 2019 to 2025). A carcinoma that arises from the lung and is characterized by the presence of malignant glandular epithelial cells. "The asparaginase plasmid and the Sleeping Beauty plasmid were co-transfected using amine-functionalized mesoporous nanoparticles into the human lung adenocarcinoma cells." (PMID 31391525, 2019). "In this study, we develop a nanoparticle delivery system to permanently integrate the asparaginase gene into the genome of human lung adenocarcinoma cells." (PMID 31391525, 2019). "Furthermore, asparaginase therapy activated autophagy in laryngeal squamous cell carcinoma, as well as lung adenocarcinoma." (PMID 41316157, 2025). "We demonstrated the asparaginase gene delivered by the nanoparticles could effectively kill two human lung adenocarcinoma cells, PC9 and A549, with great additive effect to common chemotherapy drugs." (PMID 31391525, 2019).
steatosis (3 papers, 2015 to 2025). Increased lipid within the cytoplasm of cells. "Patients undergoing treatment with asparaginase may experience a spectrum of adverse metabolic events that include hepatotoxicity and steatosis." (PMID 39798881, 2025). "Chemotherapy associated steatosis or seatohepatitis (CASH) related to 5-fluorouracil (5-FU), tamoxifen, irinotecan (IRI), cisplatin, and asparaginase may also cause macrovesicular steatosis." (PMID 26273591, 2015). "Systemic Atg7 ablation reduced liver protein synthesis and increased liver injury in vehicle-injected mice but did not further reduce liver protein synthesis, exacerbate steatosis or liver injury, or alter energy expenditure following 5 days of asparaginase exposure." (PMID 39798881, 2025).
autoimmune disease (2 papers, 2020 to 2024). A disorder resulting from loss of function or tissue destruction of an organ or multiple organs, arising from humoral or cellular immune responses of the individual to their own tissue constituents. "Consequently, asparaginase is considered to hold therapeutic potential for autoimmune diseases." (PMID 38233574, 2024).
Burkitt lymphoma (2 papers, 2019). A rare form of malignant mature B-cell non-Hodgkin lymphoma. "Both arginase and asparaginase efficiently induced cell death in a mature B cell line, Ramos, derived from a patient with Burkitt lymphoma, whereas both enzymes were relatively inefficient in inducing cell death in another such cell line, DG-75." (PMID 30578463, 2019). "Arginase or asparaginase might potentially be used to treat Burkitt lymphoma." (PMID 30578463, 2019). "As Burkitt lymphoma lymphoblasts do not normally overexpress BCL-2 or other mutations rendering them resistant to apoptosis, arginase and asparaginase may be useful in the treatment of Burkitt lymphoma." (PMID 30578463, 2019).